RHO (rhodopsin)
Description:
G protein-coupled photoreceptor that activates the G protein transducin (t) signaling pathway in response to light and is essential for image-forming vision under low-light conditions. Required for postnatal photoreceptor cell viability. Activation occurs when the covalently bound 11-cis-retinal chromophore absorbs a photon and isomerizes to all-trans-retinal, inducing a conformational change in the opsin that triggers G protein-mediated phototransduction (Probable). Signal termination occurs via receptor phosphorylation, which promotes binding of arrestin (SAG) and displacement of the G protein alpha subunit (Probable).
Synonyms: OPN2; CSNBAD1; RP4
Tractability: Small molecule: it belongs to a druggable protein family. Antibody: its Gene Ontology location is reachable by antibodies, with high confidence; UniProt predicts a signal peptide or a membrane-spanning region.
Target class: Family A G protein-coupled receptor; Membrane receptor; Opsin; Rhodopsin
Gene: Protein-coding gene on chromosome 3 (129,528,639 to 129,535,344, forward strand). Ensembl gene ENSG00000163914.
Subcellular location: Photoreceptor outer segment membrane; Membrane
Pathways (Reactome):
Sensory Perception: Activation of the phototransduction cascade; Inactivation, recovery and regulation of the phototransduction cascade; The canonical retinoid cycle in rods (twilight vision)
Signal Transduction: G alpha (i) signalling events; Opsins
Organelle biogenesis and maintenance: VxPx cargo-targeting to cilium
Gene Ontology:
Molecular function: protein binding; 11-cis retinal binding; G protein-coupled photoreceptor activity; G protein-coupled receptor activity
Biological process: absorption of visible light; G protein-coupled receptor signaling pathway; visual perception; cellular response to light stimulus; G protein-coupled opsin signaling pathway; phototransduction; phototransduction, visible light; transducin-mediated opsin signaling pathway
Cellular component: Golgi apparatus; membrane; photoreceptor disc membrane; photoreceptor inner segment; photoreceptor inner segment membrane; photoreceptor outer segment; photoreceptor outer segment membrane; plasma membrane; rod photoreceptor disc membrane; ciliary membrane; Golgi membrane; Golgi-associated vesicle membrane; cell-cell junction; sperm head plasma membrane; sperm midpiece
Genetic constraint (gnomAD): Loss-of-function variants: 21 observed, 33.22 expected, observed/expected ratio (o/e) 0.63, 90% interval 0.45 to 0.91. The upper end of that interval is the gene's LOEUF score, 0.91, which puts it in group 3 of 6, group 1 being the genes least tolerant of losing a copy. Missense variants: 414 observed, 502.64 expected, observed/expected ratio (o/e) 0.82, 90% interval 0.76 to 0.89. Synonymous variants: 211 observed, 207.14 expected, observed/expected ratio (o/e) 1.02, 90% interval 0.91 to 1.14.
Homologues: Orthologues: chimpanzee RHO (100% identical), macaque RHO (98% identical), dog RHO (95% identical), guinea pig RHO (95% identical), pig RHO (95% identical), rat Rho (95% identical), mouse Rho (95% identical), rabbit RHO (94% identical), zebrafish rho (80% identical), zebrafish rhol (74% identical), zebrafish RHO (41% identical), zebrafish exorh (26% identical). Paralogues in human: OPN1SW (45% identical), OPN1MW (45% identical), OPN1MW2 (45% identical), OPN1MW3 (45% identical), OPN1LW (44% identical), OPN3 (28% identical), OPN4 (27% identical), RRH (24% identical), OPN5 (22% identical).
Diseases named in the same sentence as RHO in open-access papers:
RHO is named in the same sentence as 177 diseases in open-access papers, as found by Europe PMC text mining. Sharing a sentence is not in itself a finding about the gene and the disease. The quoted sentences say what the papers report.
retinal degeneration (244 papers, 2007 to 2026). Degeneration of the retina. "Retinal degeneration due to the heterozygous rhodopsin P23H mutation is considered to occur relatively slowly, as only one rhodopsin allele is dysfunctional whilst the other allele is still generating functional wildtype rhodopsin protein." (PMID 41562848, 2026). "While incomplete, the rescue achieved supports the potential of monoterpenoid-based pharmacological chaperones for selected rhodopsin-linked retinal degenerations." (PMID 41938701, 2026). "Expression of glycosylation-deficient rhodopsin mutants (T4K and T17M) in Xenopus explored light-exacerbated retinal degeneration mechanisms, finding that additional disulfide bonds increased thermal stability and reduced retinal degeneration." (PMID 41210874, 2025). "Mice carrying a knock‐in of the P23H mutation of the rhodopsin gene are a well‐characterized model of retinitis pigmentosa (RP), a hereditary retinal degeneration affecting primarily rods." (PMID 40171795, 2025). "In this paper, we describe the largest cohort to date of RHO-associated RP, the spectrum of phenotypes and likely disease-causing variants, the natural history, and the molecular mechanisms underlying this retinal degeneration." (PMID 40736177, 2025). "The molecular mechanism underlying retinal degeneration caused by rhodopsin misfolding is discussed in detail in other reviews." (PMID 41009537, 2025). "Aggregation of these mutants appeared to be a primary driver of photoreceptor cell loss with the more severe aggregation profile of the G188R rhodopsin mutant observed both in vitro and in vivo correlating with a more severe retinal degeneration." (PMID 39875362, 2025). "In this paper, we describe the largest cohort to date of RHO-associated RP, the spectrum of phenotypes and likely disease-causing variants, and the molecular mechanisms underlying the retinal degeneration." (PMID 40736177, 2025). "The present findings support previous studies including our own that showed minocycline inhibited microgliosis and photoreceptor loss in mouse models of age-related retinal degeneration and P23H-1 (rhodopsin mutation) rat model of retinal degeneration." (PMID 40591415, 2025). "Rabin8 phosphorylation loss due to an NDR2 gene disruption thereby likely causes dysfunctional rhodopsin Golgi-to-cilia trafficking underlying retinal degeneration and early-onset blindness." (PMID 39774853, 2025). "In this study, we investigated the molecular and pathophysiological effects of combining circadian clock dysfunction and retinal degeneration, most importantly rhodopsin‐linked RP." (PMID 40171795, 2025). "Retinal degeneration-causing mutations often misaccumulate rhodopsin in the inner segment, nuclear layer and synaptic regions." (PMID 39871753, 2025). "As retinal degeneration progresses in P23H-1 rats, the progressive loss of photoreceptors is accompanied by shortening of the outer segments and mislocalization of rhodopsin to the inner segment region." (PMID 40231721, 2025). "In fact, it was reported that patients with pathogenic variants in some specific genes, including EYS and RHO, exhibit such patterns of retinal degeneration." (PMID 38646933, 2024). "Taken together, these results signify the therapeutic efficacy of reducing levels of RHO as a strategy in impeding retinal degeneration caused by PRPH2 pathogenic variants." (PMID 38834544, 2024). "We then tested 8-AG’s efficacy in the RhoP23H/+ knock-in mouse model of retinitis pigmentosa (RP), a different retinal degeneration model caused by rhodopsin misfolding." (PMID 38765984, 2024). "It was shown in a knock-in mice model that the E150K mutation impairs rhodopsin stabilization, which results in a progressive retinal degeneration." (PMID 36840007, 2023). "We employed another mouse model of retinal degeneration using RhoP23H/+ mice with the P23H RHO mutation, referred to as P23H mice." (PMID 37720108, 2023).
retinal degeneration (continued). "Conventional treatments have little effect in terms of the cure and prevention of retinal degeneration as a result of the wide spectrum of rhodopsin mutations." (PMID 37077319, 2023). "Arr2 is an inhibitory protein responsible for inactivation of rhodopsin and plays an essential role in terminating the phototransduction response, and a mutation of arr2 results in retinal degeneration." (PMID 36662000, 2023). "In the past two decades, enormous efforts have been directed toward developing innovative treatment methods or drugs to protect vision from retinal degeneration caused by RP, particularly rhodopsin mutations." (PMID 37077319, 2023). "Persistent rhodopsin activation can cause retinal degeneration in both a transducin-dependent manner and a transducin-independent manner." (PMID 37077319, 2023). "One study showed that FGF-15 and FGF-18 expressed from the recombinant AAV virus notably delayed retinal degeneration caused by transgenic rats expressing a P23H or Q334ter rhodopsin mutation." (PMID 37077319, 2023). "Since the first rhodopsin mutation was identified in RP patients, tremendous progress has been made toward understanding the mechanisms of retinal degeneration arising from rhodopsin mutations." (PMID 37077319, 2023). "Light-dependent acceleration of retinal degeneration in susceptible retinas has, for instance, been shown in an animal model with rhodopsin mutation." (PMID 37336979, 2023). "These advantages make ASOs great candidates for the treatment of retinal degeneration caused by rhodopsin mutations." (PMID 37077319, 2023). "P23H rhodopsin aggregation causes retinitis pigmentosa and retinal degeneration, while wild-type rhodopsin is readily degraded by ERAD." (PMID 38057493, 2023). "Rhodopsin is essential for phototransduction, and many rhodopsin mutations cause heritable retinal degenerations." (PMID 36258031, 2022). "The Opn1mw gene is essential for normal colour vision and it has been shown that its transactivation delays retinal degeneration and improves retinal function in the heterozygous rhodopsin-deficient (Rho+/−) RP mouse model." (PMID 35626712, 2022). "Retinitis pigmentosa (RP) is the most common group of inherited retinal degenerations and pathogenic variants in the Rhodopsin (RHO) gene are major cause for autosomal dominant RP (adRP)." (PMID 35893064, 2022). "The experiment was performed using a murine line bearing a mutation in the rhodopsin gene (Rho) that causes slow-progression retinal degeneration, where photoreceptor cell death starts to be detected at PN15." (PMID 36678654, 2022). "In Drosophila melanogaster, absence of PDH results in progressive light-dependent loss of rhodopsin and retinal degeneration, and the expression of RDH12 in PCRs can suppress these defects." (PMID 36555080, 2022). "Modulation of protein quality control has shown therapeutic promise in preventing retinal degeneration arising from rhodopsin mutations." (PMID 36258031, 2022). "Mutations in the photoreceptor protein rhodopsin are known as one of the leading causes of retinal degeneration in humans." (PMID 34997336, 2022). "Previous studies have reported that the onset of retinal degeneration takes at least 2 weeks in RP animal models with rhodopsin mutations." (PMID 34088267, 2021). "Coincidentally, dysfunctional Rhodopsin homeostasis underlies retinal degeneration in humans and model organisms." (PMID 34714826, 2021). "More recently, this compound has been tested as a potential therapeutic agent for the treatment of retinal degeneration associated with retinitis pigmentosa caused by rhodopsin mutations." (PMID 34069614, 2021). "Mutations in the human rhodopsin gene account for the largest portion of inherited retinal degenerations of known genetic etiology." (PMID 32123325, 2021).
retinal degeneration (continued). "Our findings demonstrate that Atf6 is required for efficient clearance of rhodopsin protein in rod photoreceptors expressing P23H rhodopsin, and that loss of Atf6 ultimately accelerates retinal degeneration in P23H-KI mice." (PMID 34381136, 2021). "In this RP model, the time to onset of retinal degeneration was less than that of previously reported RP models with other rhodopsin mutations, enabling quicker in vivo evaluation of drug efficacy." (PMID 34088267, 2021). "In this RP model, the time to onset of retinal degeneration was less than that of previously reported RP models with other rhodopsin gene mutations, enabling quicker in vivo evaluation of drug efficacy." (PMID 34088267, 2021). "Animal models exhibiting rhodopsin glycosylation deficiency are vulnerable to light-related retinal degeneration." (PMID 32795431, 2021). "Mutation at the C-terminus can block rhodopsin transport to the outer segment such that the protein accumulates in the cytoplasm, leading to retinal degeneration." (PMID 34088267, 2021). "In 1995, Drosophila was used for the first time as a model to decipher the mechanisms by which mutations in RHO caused retinal degeneration, demonstrating the great potential of this model for this group of diseases." (PMID 32349249, 2020). "In support of this conjecture, recent studies found that SARM1 promotes retinal degeneration in X-linked retinoschisis and rhodopsin-deficient mice." (PMID 33107823, 2020). "Defective rhodopsin homeostasis is one of the major causes of retinal degeneration, including the disease Retinitis pigmentosa." (PMID 31263175, 2020). "For example, many genes harboring mutations implicated in retinal degenerations characterized predominantly by night blindness–such as RHO, SLC24A1, and GNAT1–were confirmed to be selectively expressed in rods." (PMID 32555229, 2020). "Retinal degeneration has been attributed to a wide variety of causes, such as disruption of genes involved in phototransduction, biosynthesis, folding of the rhodopsin molecule, and the structural support of the retina." (PMID 32033529, 2020). "A wide variety of causes have been attributed to retinal degeneration, such as disruption of the genes involved in phototransduction, biosynthesis, folding of the rhodopsin molecule, and the structural support of the retina." (PMID 32033529, 2020). "Here, we performed a genome-wide screen to identify suppressors of retinal degeneration in a Drosophila model of adRP, carrying a point mutation in the major rhodopsin, Rh1 (Rh1G69D)." (PMID 33137101, 2020). "The combination of disintegrated Golgi and aberrant rhodopsin transportation in Hsp90α-deficient photoreceptor suggested a probable cause for the retinal degeneration." (PMID 31408169, 2020). "Another possibility is that F45L and F220C are modifying alleles, which interact with other non-rhodopsin mutations to cause retinal degeneration in adRP patients." (PMID 32371886, 2020). "We initially focused on OS disc structure as disc disorganization has been described in other models of retinal degeneration, including in heterozygous knock in mice, carrying the most common RP-causing mutation in rhodopsin, P23H." (PMID 33201897, 2020). "The EMC is critical for the stable expression of multipass transmembrane proteins such as rhodopsin, and its loss causes retinal degeneration in Drosophila and mice." (PMID 32886670, 2020). "Two rhodopsin mutations resulting in the earliest onset of retinal degeneration, rhodopsin Ter349Glu and Gln344Ter, behave in this manner." (PMID 32151065, 2020). "In fact, no mammalian homologs have been identified for any Drosophila gene involved in rhodopsin biogenesis in the ER that cause retinal degeneration when mutated." (PMID 31263175, 2020). "Rhodopsin also plays structural roles in maintaining the morphology of photoreceptor cells, therefore loss of rhodopsin in most ninaE alleles results in retinal degeneration." (PMID 31263175, 2020).
retinal degeneration (continued). "The addition of GFP to the C-terminus of the RHO protein allows direct visualization of the protein and its expression is known to cause retinal degeneration." (PMID 31824252, 2019). "AAV-mediated RHO augmentation partially rescues retinal degeneration in the well-characterized R23H transgenic mouse model, which exhibits loss-of-function evidenced by reduced rhodopsin levels." (PMID 31836750, 2019). "Failure in any step of these pathways often results in aberrant rhodopsin accumulation in a late endosomal, Rab7-positive compartment, and represents one cause of retinal degeneration." (PMID 31834921, 2019). "Defective anterograde trafficking of rhodopsin is a well-established feature associated with retinal degeneration also in the vertebrate retina." (PMID 31834921, 2019). "Hyperphosphorylation of rhodopsin results in the generation of stable rhodopsin-arrestin complexes that are internalized, activate apoptosis, and ultimately cause retinal degeneration." (PMID 30265717, 2018). "Mutations resulting in the misfolding of rhodopsin can lead to autosomal dominant retinitis pigmentosa (adRP), a progressive retinal degeneration that currently is untreatable." (PMID 29773803, 2018). "The sensitivity and quantitative capacity of the protocol were validated using wild type mice and an inherited mouse model of retinal degeneration – mice carrying rhodopsin deficiency and exhibiting progressive loss of photoreceptors." (PMID 29946119, 2018). "It is possible that the relative preservation of the implicit times of a-waves is one of characteristics of the retinal degeneration associated with mutations in the rhodopsin genes." (PMID 30581855, 2018). "In this study, we used GSK2606414A, a selective inhibitor of PERK, to further investigate the role of this branch of the UPR in retinal degeneration associated with misfolded P23H rhodopsin." (PMID 29036441, 2017). "In-frame deletions frequently caused dominant retinal degeneration associated with rhodopsin biosynthesis defects, while frameshift phenotypes were consistent with knockout." (PMID 28761125, 2017). "Retinal degeneration in the P23H-1 rat is caused by a mutation in the rhodopsin gene, but the RPE is functional and therefore able to phagocytose the OS of dead photoreceptors." (PMID 28321183, 2017). "Similar rhodopsin accumulations are seen in mutations that affect the trafficking of late endosomes to lysosomes, which causes light-dependent retinal degeneration." (PMID 26598556, 2016). "The S334ter-3 rat is a transgenic model of retinal degeneration (RD) developed to express a rhodopsin mutation similar to that found in human retinitis pigmentosa patients." (PMID 27225415, 2016). "Multiple studies have implicated the ER-UPR signaling cascade in other inherited retinal degeneration models, most notably in autosomal dominant RP (adRP) rhodopsin mutations (T17M, P23H, S334ter, rhodopsin-1)." (PMID 26987071, 2016). "T17M rhodopsin expression in rod photoreceptors leads to severe retinal degeneration and is associated with the activation of ER stress related Unfolded Protein Response (UPR) signaling." (PMID 27144303, 2016). "In this study, we found that KUS121, one of the VCP modulators, effectively protects photoreceptors both morphologically and functionally, in two animal models of retinal degeneration, rd12 mice and RP rabbits with a rhodopsin (Pro347Leu) mutation." (PMID 27503804, 2016). "This mutant, like the T17M RHO mutant, represents a Class II mutation and leads to dramatic retinal degeneration." (PMID 27144303, 2016). "Rhodopsin, a naturally-occurring photoreceptor protein that has been implicated retinal degenerations is expressed adjacent to the RPE and was clearly visible in our human retinal sections." (PMID 27660801, 2016).